TOP2A (DNA topoisomerase II alpha)
Diseases named in the same sentence as TOP2A in open-access papers (continued):
Sharing a sentence is not in itself a finding about the gene and the disease.
neurofibroma (2 papers, 2017 to 2024). An intraneural or extraneural neoplasm arising from nerve tissues and neural sheaths. "Human MPNST cell lines express higher levels of TOP2A than human neurofibroma cell lines and show higher sensitivity to doxorubicin." (PMID 38448751, 2024). "Transcriptome data analyses have shown that TOP2A was among the most upregulated genes in MPNSTs when compared to benign neurofibromas." (PMID 28813519, 2017). "The transcript levels of BRD4, EZH2 and TOP2A were determined in paired formalin-fixed paraffin-embedded (FFPE) neurofibroma/MPNST samples derived from the same NF1 patient and in a set of plexiform neurofibromas, atypical neurofibromas and MPNST." (PMID 28813519, 2017). "In both panels TOP2A mRNA expression was clearly induced in MPNST when compared to the levels detected in plexiform neurofibromas." (PMID 28813519, 2017). "When we determined the sensitivity of our neurofibroma and MPNST cell line panel for doxorubicin we observed that the MPNST cell lines exhibited the highest sensitivity in agreement with their higher TOP2A levels." (PMID 28813519, 2017). "In the cell line panel TOP2A mRNA levels in the MPNST cell lines were mostly equal or lower than the levels measured in the neurofibroma cell line Hs53.T, only the MPNST 90-8TL cell line exhibited relatively high TOP2A levels." (PMID 28813519, 2017). "In this study we analyzed the expression level of three potential drug targets BRD4, EZH2, and TOP2A in selected human MPNST and neurofibroma samples from the Erasmus MC tissue bank." (PMID 28813519, 2017). "To verify whether TOP2A expression levels are increased in MPNST as was reported in the literature we determined the TOP2A mRNA levels in our paired FFPE and fresh frozen plexiform neurofibroma/MPNST sample sets." (PMID 28813519, 2017).
neutropenia (2 papers, 2015 to 2023). A decrease in the number of neutrophils found in the blood. "Recent studies show that MKI67 and TOP2A were contained within a network of genes that are upregulated in NK-cell repertoires in patients with neutropenia, which is associated with apoptosis and cell cycle." (PMID 37834393, 2023).
ovarian serous cystadenocarcinoma (2 papers, 2022). A malignant serous cystic epithelial neoplasm arising from the ovary. "The 215 AA in the Tudor domain of TOP2A protein (T215P) showed the highest mutation frequency, which was detected in 7 ovarian serous cystadenocarcinoma cases." (PMID 35873470, 2022). "Then, the potential association between TOP2A genetic alteration and the clinical survival prognosis of ovarian serous cystadenocarcinoma patients was analyzed based on these seven ovarian serous cystadenocarcinoma cases detected using the cBioportal For Cancer Genomics online tool." (PMID 35873470, 2022).
pancreatic ductal adenocarcinoma (2 papers, 2020 to 2023). An infiltrating adenocarcinoma that arises from the epithelial cells of the pancreas. "Many of those genes were related to various kinds of neoplasia progression (Tpx2, Id3, Top2a, Dab2, Mecom, Nrp1107–112), including pancreatic ductal adenocarcinoma, or pancreatitis (Gsn113)." (PMID 37689751, 2023).
pancreatitis (2 papers, 2023 to 2025). Inflammation of the pancreas. "Further investigations, including differential expression analysis and machine learning techniques, revealed six significant diagnostic markers for pancreatitis: RAP1GDS1, TOP2A, ADK, POLL, CD44, and CD4." (PMID 40787634, 2025). "In our study, we identified key hypoxia-related genes—RAP1GDS1, TOP2A, ADK, POLL, CD44, and CD4—in pancreatitis samples using methods such as WGCNA, XGBoost, and RF algorithms." (PMID 40787634, 2025). "We then conducted qRT-PCR on serum samples from five pancreatitis patients and five healthy controls to examine the expression levels of RAP1GDS1, TOP2A, ADK, POLL, CD44, and CD4." (PMID 40787634, 2025).
papillary renal cell carcinoma (2 papers, 2019 to 2022). A rare subtype of renal cell carcinoma, arising from the renal tubular epithelium and showing a papillary growth pattern, which typically manifests with hematuria, flank pain, palpable abdominal mass or nonspecific symptoms, such as fatigue, weight loss or fever. "Interestingly, these KNL1-related molecules (e.g., BUB1, ASPM, TOP2A) have been implicated in immune infiltration in papillary renal cell carcinoma in another report." (PMID 36685823, 2022).
rectal tumors (2 papers, 2017 to 2021). "We also verified TOP2A copy number gains and increased expression in rectal tumors." (PMID 34771654, 2021).
renal carcinoma (2 papers, 2023 to 2024). A carcinoma arising from the epithelium of the renal parenchyma or the renal pelvis. "Using qRT-PCR, Western blotting, and immunohistochemical staining, we verifed that TOP2A expression was elevated in RCC cell lines and in renal cancer tissue compared with human renal tubular epithelial cells and normal renal tissue, respectively." (PMID 37818158, 2023).
skin cancer (2 papers, 2022 to 2024). "The results showed that, in breast, kidney, liver, lung, prostate, and skin cancers, TOP2A expression was significantly upregulated in the tumor than in the normal control tissues; as well as in the metastatic versus the tumor tissues." (PMID 35873470, 2022).
skin cutaneous melanoma (2 papers, 2022). "Meanwhile, TOP2A mRNA expression was also found to be significantly increased in metastasis skin cutaneous melanoma than in the primary skin cutaneous melanoma." (PMID 35873470, 2022).
squamous intraepithelial lesions (2 papers, 2007 to 2022). "A few have reported role of ProExC with Topoisomerase II alpha (TOP2A) and minichromosome maintenance protein 2 (MCM2) in detection of cervical high-grade squamous intraepithelial lesions from cytologic samples." (PMID 17374161, 2007).
thyroid cancer (2 papers, 2018 to 2019). "Several mechanisms for the anticancer effects of DOX in the treatment of thyroid cancer have been proposed, of which inhibition of DNA synthesis by poisoning topoisomerase II (TOP2A) and intercalation with DNA are well described." (PMID 30183420, 2018). "TCGA data suggested that the expression levels of TOP2A, TYMS, FEN1, and PRC1 genes were also upregulated in other histological subtypes of thyroid carcinoma." (PMID 30774662, 2019). "High expression of TOP2A, TYMS, FEN1, PRC1, or UBE2C gene significantly decreased disease-free survival of patients with other thyroid carcinomas." (PMID 30774662, 2019). "Further survival analysis showed that high expression of TOP2A, TYMS, FEN1, PRC1, or UBE2C gene significantly decreased disease-free survival of patients with other thyroid carcinomas." (PMID 30774662, 2019). "Survival analysis indicated that high expression of TOP2A, TYMS, FEN1, PRC1, or UBE2C gene significantly decreased disease-free survival of patients with other thyroid carcinomas." (PMID 30774662, 2019). "Results suggested that the expression levels of hub genes, TOP2A, TYMS, FEN1, and PRC1, were also upregulated in at least one histological subtype of thyroid carcinoma." (PMID 30774662, 2019).
acute kidney injury (1 paper, 2023). Sudden and sustained deterioration of the kidney function characterized by decreased glomerular filtration rate, increased serum creatinine or oliguria. "MKi67 and TOP2A have been shown to modulate DNA replication of cell cycle, and participate in renal repair after acute kidney injury." (PMID 37460555, 2023).
adenoma (1 paper, 2013). A neoplasm arising from the epithelium. "Array data mining found that genes such as Ccnb1, Igfbp3, Nusap1, Pttg1, Racgap1, Top2a, Tpx2, which are associated with the aggressive behaviour of various human tumors, including PAs, and proto-oncogenes such as Ect2, Kit, Kras, Lyn, Ret are up-regulated in rat adenomas." (PMID 23756599, 2013).
adenopathy (1 paper, 2024). "The majority of patients (N = 47; 63.5%) did not have clinically involved adenopathy (N0) at inclusion (N = 23 TOP2A + and N = 24 TOP2A-)." (PMID 38453781, 2024).
Allergy (1 paper, 2021). An allergy is an immune response or reaction to substances that are usually not harmful. "We found that SMC4 and FANCB are independent predictors for survival, and TOP2A, mold/dust allergy and preoperative corticosteroids are independent predictors for the PFI of LGG patients." (PMID 34868977, 2021).
bladder tumour (1 paper, 2022). "To determine whether TOP2A and RRM1 expression plays a role in tumour drug sensitivity, we measured the mRNA and protein levels of TOP2A and RRM1 in the bladder tumour cell lines BIU-87, KK47 and human embryonic bladder tissue derived cells CCC-HB-2 by RT-qPCR and Western blot analysis." (PMID 35711974, 2022).
Bloom syndrome (1 paper, 2015). Bloom syndrome (BSyn) is a rare chromosomal breakage syndrome characterized by a marked genetic instability associated with pre- and postnatal growth retardation, facial sun-sensitive telangiectatic erythema, increased susceptibility to infections, and predisposition to cancer. "Yeast Top2 binds the Sgs1 helicase and mammalian Top2α interacts with BLM, the Bloom Syndrome helicase, and RNA helicase A, orthologous to MLE." (PMID 26053165, 2015).
bone metastasis (1 paper, 2023). Transfer of a neoplasm from its primary site to bones. "In conclusion, our study sheds light on the significance of TOP2A in LIHC bone metastasis and provides a new target and biomarker for the treatment and prognosis of LIHC bone metastasis." (PMID 37980167, 2023).
brain glioma (1 paper, 2025). A malignant glioma that involves the brain. "According to the TOP2A expression of brain gliomas obtained in the TCGA database, we divided them into high-expression groups and low-expression groups (according to median) to obtain their gene trend maps." (PMID 41284119, 2025).
Burkitt lymphoma (1 paper, 2014). A rare form of malignant mature B-cell non-Hodgkin lymphoma. "Altogether, levels of TOP2A in BLs are elevated relative to immortalized B cells and that high dose doxorubicin in addition to standard CHOP therapy may improve Burkitt's lymphoma patient outcome through TOP2A mediated doxorubicin response." (PMID 24586784, 2014).
chronic hepatitis C (1 paper, 2022). "ROC curve analysis reveals the power of the relative expression levels of LINC01564, RAMS11, CBX4 and TOP2A in discriminating HCC patients from HCV group, suggesting the possible role of these molecular non-invasive markers in early diagnosis of HCC in chronic hepatitis C cases." (PMID 36672564, 2022).
dysplasia (1 paper, 2021). A usually neoplastic transformation of the cell, associated with altered architectural tissue patterns. "In addition, it has been reported that telomerase expression was increased in LSIL and HSIL compared to NSIL samples, and increased expression of MCM2 and TOP2A (ProExC) was correlated with dysplasia and severity of cervical lesions." (PMID 33413211, 2021).
endometriosis (1 paper, 2022). The growth of functional endometrial tissue in anatomic sites outside the uterine body. "Previous studies have shown that the expression of TOP2A was significantly lower in the endometriosis group than in the control group, indicating that the expression pattern of TOP2A in endometriosis is the same as that in RIF in our study." (PMID 36138481, 2022).
ependymoma (1 paper, 2018). A WHO grade II, slow growing tumor of children and young adults, usually located intraventricularly. "WP744 (berubicin), another TOP2A inhibitor able to penetrate the blood-brain barrier, has been tested in primary CNS malignancies with some success; however, additional studies of this agent in ependymoma may be warranted." (PMID 29487694, 2018). "Elevated TOP2A expression in ependymoma has not been reported previously; however, etoposide, a TOP2A inhibitor, has been used to treat recurrent ependymoma with very modest clinical results, likely because the agent has meager CNS penetration." (PMID 29487694, 2018).
HCMV infection (1 paper, 2018). "We found that, after HCMV infection, the expression of miR-144-3p decreased, whereas the expression of TOP2A increased." (PMID 30544723, 2018). "The high mRNA and protein expression (TOP2A expression level > 1) of TOP2A was verified in these two cell lines after HCMV infection." (PMID 30544723, 2018).
hepatitis B (1 paper, 2022). "The normal group-hepatitis B, hepatitis B-hepatitis B-related hepatocellular carcinoma, and hepatitis C-related cirrhosis-hepatitis C-related hepatocellular carcinoma data have 2 common targets CDK1 and TOP2A with the predicted targets of YZHG." (PMID 35342754, 2022). "The data of normal group-hepatitis B, hepatitis B-hepatitis B-related hepatocellular carcinoma, and hepatitis C-related cirrhosis-hepatitis C-related hepatocellular carcinoma all had two common targets CDK1 and TOP2A with YZHG putative targets." (PMID 35342754, 2022).
influenza (1 paper, 2021). An acute viral infection of the respiratory tract, occurring in isolated cases, in epidemics, or in pandemics; it is caused by serologically different strains of viruses (influenzaviruses) designated A, B, and C, has a 3-day incubation period, and usually lasts for 3 to 10 days. "Cluster IV contained several immunoglobulin genes, in addition to MKI67 (Ki67), TOP2A and BIRC5 (Survivin), which are associated with proliferation, likely representing a plasmablast signature as has been reported at Day 7 after immunization with the influenza vaccine." (PMID 33720973, 2021).
invasive carcinoma (1 paper, 2015). A carcinoma that is not confined to the epithelium, and has spread to the surrounding stroma. "TOP2A expression was associated with DCIS, usually high grade and associated with invasive carcinoma." (PMID 26657114, 2015). "The majority of cases expressing TOP2A were high grade (none were low grade) and usually associated with invasive carcinoma." (PMID 26657114, 2015). "Interestingly, high expression of p-mTOR was observed in all PNL with lower expression in DCIS and invasive carcinoma while the opposite expression pattern was observed for TOP2A." (PMID 26657114, 2015).
ischemic stroke (1 paper, 2021). A stroke disorder caused by obstruction of blood flow to the brain, due to thrombotic (local blood clot formation) or embolic (due to a blood clot or other material traveling from another site) event. "Ultimately, seven downregulated hub genes (including Mki67, Cdk1, Tpx2, Cenpf, Ccnb2, Prc1, and Top2a) were identified as key genes regulated by EA treatment in ischemic stroke by PCR validation." (PMID 34566862, 2021). "Therefore, EA might exert neuroprotection in ischemic stroke by inhibiting reactive astrocyte and microglial (Mki67, Top2a, and Cenpf as markers) proliferation." (PMID 34566862, 2021).
laryngeal carcinoma (1 paper, 2018). Carcinoma that arises from the laryngeal epithelium. "Increased methylation levels of promoters of TOP2A (DNA topoisomerase II alpha), PLXDC2 (plexin domain containing 2), ETNK2 (ethanolamine kinase 2), GFI1 (growth factor independent 1 transcriptional repressor), and IL12B (interleukin 12B) were detected in radioresistant laryngeal cancer cells." (PMID 29439529, 2018).
latent infection (1 paper, 2021). "The increase in latent infection after knockdown of TOP2A and HNRNPH1 was coupled with a decrease in productive infection." (PMID 34194479, 2021). "On the other hand, a dramatic increase in latent infection was seen after knockdown of TOP2A, SRP14, HNRNPH1, DDX1, and HNRNPL (blue bars)." (PMID 34194479, 2021).
leiomyosarcoma (1 paper, 2025). An uncommon, aggressive malignant smooth muscle neoplasm, usually occurring in post-menopausal women. "In stage I leiomyosarcomas, higher TOP2A expression was associated with worse survival at both the RNA and protein levels." (PMID 41162745, 2025). "A significant proportion of leiomyosarcomas exhibited high or moderate TOP2A protein expression (43/56; 77%)." (PMID 41162745, 2025). "Both TOP2A and CDK1 were among the top 25 differentially expressed genes and were overexpressed in leiomyosarcomas." (PMID 41162745, 2025). "Our results indicate both TOP2A and CDK1 as potential prognostic biomarkers in uterine leiomyosarcomas." (PMID 41162745, 2025). "Notably, high expression of both TOP2A and CDK1 independently predicted worse survival in uterine leiomyosarcoma patients at all stages." (PMID 41162745, 2025).
leukopenia (1 paper, 2024). "Both typical (e.g., Doxorubicin, Etoposide) or atypical (e.g., Vosaroxin) Top2α poisons share very similar clinical safety profiles, with the most commonly observed adverse events (AE) being leukopenia and nausea/vomiting." (PMID 39062087, 2024).
liver steatosis (1 paper, 2025). "While our findings and previous literature suggest potential mechanisms by which Smpd3, Dtl, Cdc6, Top2a, and Mki67 contribute to liver steatosis, further study is needed to clarify their precise roles." (PMID 40687776, 2025). "The present study identified five genes (Smpd3, Dtl, Cdc6, Top2a, and Mki67) as potential mediators in the development of WD-induced liver steatosis." (PMID 40687776, 2025).
lobular carcinomas (1 paper, 2025). "Notably, our series, despite partial representation of various histological subtypes, showed no significant results, although TOP2A was altered in 91% of mucinous carcinomas and 33% of lobular carcinomas." (PMID 40243780, 2025).
mammary adenocarcinomas (1 paper, 2025). "In this study, we confirmed the expression levels of HIF-1α, IGF-1R and TOP2A proteins in mammary adenocarcinomas tissue." (PMID 40969744, 2025).
mantle cell lymphoma (1 paper, 2007). Mantle cell lymphoma is a rare form of malignant non-Hodgkin lymphoma affecting B lymphocytes in the lymph nodes in a region called the ``mantle zone''. "Studies show TOP2A (gene Hs.156346) is a proliferation marker, indicator of drug sensitivity, and prognostic factor in mantle cell lymphoma." (PMID 17316436, 2007).
metastatic prostate carcinoma (1 paper, 2015). A carcinoma that arises from the prostate gland and has spread to other anatomic sites. "In line with our mouse data, human metastatic prostate cancer exhibited significantly increased mRNA expression of Top2a compared to primary tumors (p<0.0001)." (PMID 25605014, 2015).
myelogenous leukemia (1 paper, 2015). "Resistance to TOP2A poisons, observed in clinically refractory tumors, and development of secondary cancers, such as myelogenous leukemia, as a result of de novo rearrangements, are the major limitations of anti-TOP2A therapy." (PMID 26560244, 2015).
Obesity (1 paper, 2022). Accumulation of substantial excess body fat. "Several hub genes, such as TOP2A, CENPF, TYMS, AURKA, KIF4A, and KIF20A, are related to the cell cycle and DNA replication, implicating the close relationship between obesity and cancer." (PMID 36232337, 2022).
pancreatic neuroendocrine tumor (1 paper, 2019). Pancreatic endocrine tumor, also known as pancreatic neuroendocrine tumor (PNET), describes a group of endocrine tumors originating in the pancreas that are usually indolent and benign, but may have the potential to be malignant. "In pancreatic neuroendocrine tumors, TOP2A was also identified as one of hub genes by gene microarray analysis." (PMID 31412643, 2019).
peripheral T-cell lymphoma (1 paper, 2022). "Expression of nm23, TOP2A, and VEGF are potential prognostic biological factors in peripheral T-cell lymphoma." (PMID 36531013, 2022).
pneumonia (1 paper, 2025). An acute, acute and chronic, or chronic inflammation focally or diffusely affecting the lung parenchyma, caused by an infection in one or both of the lungs (by bacteria, viruses, fungi, or mycoplasma.). "The downregulation of apoptosis-related genes such as TOP2A and RAD51 may promote cell survival and tissue repair, contributing to the recovery from pneumonia." (PMID 41000417, 2025).